ETV7 (ETS variant transcription factor 7)
Diseases named in the same sentence as ETV7 in open-access papers (continued):
Sharing a sentence is not in itself a finding about the gene and the disease.
melanoma (5 papers, 2020 to 2025). A malignant, usually aggressive tumor composed of atypical, neoplastic melanocytes. "A similar association between ETV7 and survival time was also observed in both male and female patients, patients with different T, N, and M stages, and patients with melanoma at the early (p = 0.0047) or advanced (p = 0.015) stage." (PMID 33424867, 2020). "ETV7 expression is hampered in melanoma, potentially regulating the immune microenvironment; hence, ETV7 has been recognized as an independent and reliable predictor of prognosis in melanoma." (PMID 38200280, 2024). "An extensive analysis of regulatory elements in the immune response to cancer types revealed ETV7 as strong regulator of the T cell receptor signaling pathway, and thus, ETV7 is a diagnostic marker of CD8+ T cell infiltration in melanoma and urothelial cancer." (PMID 37303712, 2023). "Prognostic analysis of these DEGs in the TCGA_SKCM and GSE65904 data sets consistently showed that only ETV7 had significant prognostic relevance in melanoma." (PMID 33424867, 2020). "Our results indicate that ETV7 is markedly downregulated in melanoma, and low ETV7 expression is related to the poor prognosis of SKCM patients." (PMID 33424867, 2020). "Low ETV7 expression was correlated with a significantly short OS in melanoma patients younger than 60 y (p = 0.0017) or older than 60 y (p=0.031)." (PMID 33424867, 2020). "All phenotypic and functional markers of T cells—CD3E, CD4, CD8B, FOXP3, GZMB, PRF1 and TBX21—were expressed at higher levels in melanoma patients with high ETV7 expression." (PMID 33424867, 2020). "A systematic analysis of the ETS family in melanoma identified an essential role of ETV7 in regulating the immune microenvironment of the disease." (PMID 33424867, 2020). "Melanoma patients with high ETV7 expression had significantly higher immune scores than those with low ETV7, suggesting higher immune cell infiltration in the tumor microenvironment." (PMID 33424867, 2020). "The results obtained from the present study, combined with other studies, highly suggest that ETV7 can have an essential role in T cell differentiation, proliferation, infiltration, and activation in melanoma." (PMID 33424867, 2020). "To understand the function of ETV7 in melanoma, we first identified the ETV7related genes, which were defined as those exhibiting strong correlation (coefficient >= 0.5, p < 0.05) with ETV7 at the transcriptional level in melanoma." (PMID 33424867, 2020). "We found that ETV7 was the only differentially expressed gene with significant prognostic relevance in melanoma." (PMID 33424867, 2020). "Recent study reviewed that the ETV7 was a crucial prognostic factor in melanoma, which could potentially regulate the immune microenvironment, but its results from OS is opposite from our study." (PMID 34926692, 2021). "It is reported that ETV7 regulates the immune microenvironment in melanoma." (PMID 34926692, 2021). "Indeed, when the infiltration of various immune cells in melanoma was estimated, ETV7 showed a strong positive correlation with the infiltration of CD8+ T cells." (PMID 33424867, 2020). "Moreover, IFNγ signatures (CXCL10, CXCL9, IDO1, IFNG, and STAT1) and myeloid lineage phenotypic and functional markers (CD14, CD163, CD33, and CD68) were also significantly increased in melanoma patients with high ETV7." (PMID 33424867, 2020). "Moreover, melanoma patients with high ETV7 showed significantly longer disease-specific survival (DSS) than those with low ETV7 (p < 0.0001)." (PMID 33424867, 2020). "We then investigated the prognostic relevance of ETV7 in different subgroups of melanoma patients." (PMID 33424867, 2020). "Indeed, all patients in various subgroups of melanoma with low ETV7 expression showed a significantly shorter OS than those with high ETV7 expression." (PMID 33424867, 2020).
melanoma (continued). "In addition, data from the GSE19234 data set showed that melanoma patients with low ETV7 had significantly shorter survival time since metastasis (p = 0.045)." (PMID 33424867, 2020). "Bioinformatics tools were used to characterize the function of ETV7 in melanoma." (PMID 33424867, 2020). "Thus, ETV7 can potentially regulate the immune microenvironment in melanoma." (PMID 33424867, 2020). "In melanoma, several ETS TFs, including FLI1, SPI1, ELF4, ETV7, SPIB, and SPIC, are expressed at higher levels in Cluster A patients, whereas ETV5, ETV4, ELK1, ERF, and ETV2 showed increased expression in Cluster B patients." (PMID 41502516, 2025). "The mechanism by which ETV7, a member of the ETS family, regulates the immune process and response in melanoma has yet to be determined." (PMID 33424867, 2020). "In particular, ELK3, ETS1, ETV1, ETV4, ETV5, and SPI1 were significantly upregulated in melanoma, whereas EHF, ELF3, ELF5, ERG, ETS2, ETV7, and SPDEF were significantly downregulated in the tumor." (PMID 33424867, 2020). "As a member of the ETS transcription factor family, ETV7 in melanoma has not been previously investigated." (PMID 33424867, 2020). "ETV was highly expressed in normal skin and showed markedly decreased expression in melanoma; thus, not all melanoma cells might be expected to express ETV7." (PMID 33424867, 2020). "Indeed, when the infiltration of various immune cells was estimated, the ETV7 showed strong positive correlation with high fraction of T cell CD8, T cell memory activated, T cell follicular helper and macrophages M1, which is similar to the previous study in melanoma." (PMID 34926692, 2021).
bladder cancer (4 papers, 2020 to 2025). "Of note, elevated expression of ETV7 has been linked to B lymphomagenesis, hematopoietic malignancy, hepatocellular carcinoma, and bladder cancer." (PMID 38200280, 2024). "ETV7 regulates the immune microenvironment and, thus, is a poor prognostic factor for bladder cancer." (PMID 38200280, 2024). "In cisplatin-resistant bladder cancer cell lines, FLRT2, HOXC5, SCD, GRM7, HMGA1, ETV7, and SCO2 were highly expressed, while EMP1, SERPINA6, and ZNF124 exhibited lower expression levels." (PMID 39744172, 2025). "ETV7 is a vital member of the ETS family, but its role in bladder cancer has been rarely reported." (PMID 34926692, 2021).
nasopharyngeal carcinoma (3 papers, 2019 to 2024). A carcinoma arising from the nasopharyngeal epithelium. "In nasopharyngeal carcinoma, ETV7 overexpression attenuates ectopic Snail expression or hypoxia-induced cell migration and invasion." (PMID 38200280, 2024). "In contrast, it has been shown that ETV7 functions as a tumor suppressor in nasopharyngeal carcinoma by hindering serine protease inhibitor clade E member 1 (SERPINE1) expression." (PMID 38200280, 2024). "This is consistent with an earlier study demonstrating ETV7-mediated downregulation of SERPINE1 expression and an associated survival benefit in patients with nasopharyngeal carcinoma." (PMID 31827722, 2019). "Most ETS-transcription factors are aberrantly activated or repressed in tumorigenesis, and ETV7, which encodes TEL2, has been shown to downregulate SERPINE1 in nasopharyngeal cancer." (PMID 31827722, 2019). "ETV7 has earlier been reported to act as a hematopoietic oncoprotein; however, three recent studies found that the gene could suppress the proliferation, migration, and invasion of some solid tumors such as oral squamous cell carcinoma and nasopharyngeal carcinoma." (PMID 33424867, 2020).
ovarian carcinoma (3 papers, 2021 to 2022). A malignant neoplasm originating from the surface ovarian epithelium. "Currently, although numerous molecular subtyping has been developed in ovarian cancer, such as IFNG, CD30, CXCL13, PRF1 GBP1, and ETV7 CTLA-4, they provided limited prognostic information or are not validated in the clinical samples." (PMID 36157232, 2022).
viral infections (3 papers, 2021 to 2025). "Pieces of evidence from computational studies in cancer, as well as the already-known role of ETV7 in viral infections, indicate a potential function for ETV7 in cancer immunity and inflammation." (PMID 37041130, 2023). "This gene set includes interferon-induced genes that encode antiviral proteins (OAS proteins), chemokine families (CXCL), interferon Induced proteins with tetratricopeptide repeats (IFITs) known to confer immunity against viral infections and transcription factors (XAF1, ETV7)." (PMID 41327031, 2025).
hepatocellular carcinoma (2 papers, 2020 to 2023). A malignant tumor that arises from hepatocytes. "For example, ETV7 was found to be up-regulated in 85% of medulloblastoma cases, and another study identified ETV7 as one of the 10 most up-regulated proteins in hepatocellular carcinoma." (PMID 37041130, 2023). "IRF1, PSMB9, TAP1, ETV7, and PSMB10 were related to CD8+ T cell infiltration proportion in thyroid carcinoma, breast invasive carcinoma, head and neck squamous cell carcinoma, hepatocellular carcinoma, lung adenocarcinoma, and skin cutaneous melanoma." (PMID 33330025, 2020).
leukemia (2 papers, 2014 to 2019). A malignant (clonal) hematologic disorder, involving hematopoietic stem cells and characterized by the presence of primitive or atypical myeloid or lymphoid cells in the bone marrow and the blood. "ETV7 is a human oncogene that causes leukemia when expressed in murine bone marrow." (PMID 24357328, 2014). "However, once our ETV7Tg mice were crossed with oncogenic Ptenfl/fl;Mx1-Cre mice, ETV7 accelerated PTENΔ/Δ leukemia." (PMID 30478527, 2019). "Taken together, these data suggest that ETV7 might play an important role during normal hematopoiesis and leukemia." (PMID 24357328, 2014). "We and others independently identified the ETS transcription factor ETV7, which is highly homologous to ETV6/TEL, a frequent target of chromosomal translocation in human leukemia." (PMID 30478527, 2019).
myeloproliferative disease (2 papers, 2019 to 2021). "ETV7 was shown to cooperate with Eμ-MYC in promoting B-lymphomagenesis and the forced expression of ETV7 in mouse bone marrow was shown to cause myeloproliferative diseases, even if with a long latency, suggesting TEL2 as a bona fide oncogene." (PMID 34315857, 2021). "In the mouse, retroviral transduction of ETV7 in BM caused myeloproliferative disease and in combination with Myc over expression accelerated B-cell lymphoma development." (PMID 30478527, 2019).
colorectal cancer (1 paper, 2024). A primary or metastatic malignant neoplasm that affects the colon or rectum. "ETS variant transcription factor 7 (ETV7) participates in the development of malignant tumors, whereas its involvement in colorectal cancer (CRC) is less clear." (PMID 38200280, 2024).
Ewing sarcoma (1 paper, 2023). A small round cell tumor that lacks morphologic, immunohistochemical, and electron microscopic evidence of neuroectodermal differentiation. "Notably, ETV7, the homologue of ETV6, is not expressed in Ewing sarcoma cells, and we did not observe strong changes in the expression of other ETS TFs with ETV6 loss." (PMID 36658220, 2023).
influenza (1 paper, 2022). An acute viral infection of the respiratory tract, occurring in isolated cases, in epidemics, or in pandemics; it is caused by serologically different strains of viruses (influenzaviruses) designated A, B, and C, has a 3-day incubation period, and usually lasts for 3 to 10 days. "Interestingly, ELF1 transcriptionally program cells with potent antiviral activity and ETV7 targeted antiviral ISGs crucial for IFN-mediated control of viruses, including influenza and SARS-CoV-240,41." (PMID 35017649, 2022).
Lyme borreliosis (1 paper, 2024). "A second GWAS published shortly later replicated the rs2232950 hit and identified rs1061632—an expression quantitative trait locus for KCTD20 and ETV7, as associated with Lyme borreliosis." (PMID 39140751, 2024).
lymphoid leukemia (1 paper, 2019). A malignant lymphocytic neoplasm of B-cell or T-cell lineage involving primarily the bone marrow and the peripheral blood. "In contrast, ETV7 is frequently upregulated in a variety of human cancers, including hematopoietic malignancies, in which ETV7 is overexpressed in 70% of myeloid and lymphoid leukemia." (PMID 30478527, 2019).
myeloid leukemia (1 paper, 2019). A clonal proliferation of myeloid cells and their precursors in the bone marrow, peripheral blood, and spleen. "Therefore, we concluded that the ETV7Tg mice are not tumor-prone, despite the observation that a high percentage of human tumors overexpress ETV7, including 70% of childhood acute lymphoid and myeloid leukemia." (PMID 30478527, 2019).
myeloma (1 paper, 2025). "According to the research results of cell type-specific regulatory activity, the most activated TFs in these myeloma cell subgroups included ETV7(C0 GNB2L1+ NK cells), TAF1(C1 RACK1+ NK cells), POU2F2(C2 HNRNPH1+ NK cells), and RUNX2(C3 ATP5E+ NK cells)." (PMID 40454289, 2025).
tumor (21 papers, 2014 to 2025). "AP2S1, P3H4 (SC65), SPAG4, PLA2G2F, PTPN6, RAC3, and ETV7 were identified as candidate tumor-associated antigens." (PMID 35814377, 2022). "Elevated ETV7 expression has been associated with several tumor types; however, the role of ETV7 in cancer has been poorly investigated." (PMID 34315857, 2021). "LAMP3 is a lysosomal membrane associated protein important in dendritic cells and potentially involved in tumor invasion, while ETV7 is a transcription factor associated to cell proliferation and tumorigenesis." (PMID 25401416, 2014). "Finally, CIBERSORT results proved that the high and low expression of ETV7 also caused significant differences in the tumor immune microenvironment of patients." (PMID 34926692, 2021). "Therefore, ETV7 depletion may cause the inactivation of mTOR3 and lead to tumor cell death after treatment." (PMID 33424926, 2020). "The investigators reported that ETV7 belonged to a rapamycin-insensitive mechanistic target of rapamycin kinase (mTOR) complex, which promoted tumor onset and accelerates tumor penetrance." (PMID 38200280, 2024). "In contrast, knockdown of EVT7 induced opposite effects, indicating the tumor-promoting role of ETV7 in CRC progression." (PMID 38200280, 2024). "Previous studies showed that ETV7 promotes tumor progression by acting on various molecular and cellular pathways." (PMID 37041130, 2023). "It is important to emphasize that the effect of Neu1+/− is not in the generation of RMS, but rather in its pleomorphic transformation once the tumor is initiated; while ETV7 expression is promoting a high incidence of RMS formation in Ptch1+/− mice." (PMID 36127469, 2022). "This study identified tumor microenvironment-related genes, including monokine induced by gamma interferon (MIG or CXCL9), E26 transformation-specific variant 7 (ETV7), guanylate binding protein 4 (GBP4), and CD3 epsilon chain (CD3E)." (PMID 34054929, 2021). "In contrast with these observations, ETV7 was shown to act as tumor suppressor in nasopharyngeal carcinoma by repressing SERPINE1, and its downregulation was observed in drug-resistant cancer cells." (PMID 34315857, 2021). "Online databases of UALCAN and HPA indicated that ETV7 was overexpressed in tumors and negatively correlated with tumor severity." (PMID 34926692, 2021). "We have recently published a novel mechanism of ETV7-mediated resistance to the chemotherapeutic agent Doxorubicin which involves the downregulation of DNAJC15 tumor suppressor leading to an increased expression of ABCB1 efflux pump." (PMID 34315857, 2021). "Overall, this study suggests a mechanism whereby NICD mediated SERPINE1 downregulation via ETV7 contributes to several of the tumour-suppressive features of NOTCH1 signaling." (PMID 31827722, 2019). "To examine the oncogenic potential of ETV7 in vivo, we crossed ETV7Tg+/WT mice with tumor-prone mouse models." (PMID 30478527, 2019). "Intriguingly, ETV7 slightly shortened the tumor onset of Arf−/− mice but Ink4aArf−/− and Ink4aArf−/−ETV7Tg+/WT mice showed completely overlapping survival curves." (PMID 30478527, 2019). "Cellular verification demonstrated that GBP1 and ETV7 may act as tumor suppressors in HGSOC, whereas CXCL13 may promote cell proliferation and migration." (PMID 32544083, 2020). "There is growing evidence of a significant role of ETV7 in the mTOR signaling pathway, which involves the assembly of the mTOR3 complex to stimulate cell proliferation and prevent cell damage by rapamycin, a common anti-tumor agent." (PMID 33424926, 2020). "However, ETV7 greatly reduced the tumor-free lifespan of mice, indicating that ETV7 cooperatively accelerated the onset of PtenΔ/Δ leukemogenesis." (PMID 30478527, 2019). "Interestingly, the expression of ETV7 correlated with the tumor’s aggressiveness." (PMID 37041130, 2023).